PCK1 (phosphoenolpyruvate carboxykinase 1)
Diseases named in the same sentence as PCK1 in open-access papers (continued):
Sharing a sentence is not in itself a finding about the gene and the disease.
diabetes (continued). "PCK1, also known as cytoplasmic phosphoenolpyruvate pyruvate (PEPCK-C), is a multifunctional gene related to glycogen isogenesis, glycerol isogenesis, reproduction and female fertility, obesity and diabetes." (PMID 34641739, 2021). "The importance of PCK in the pathophysiology of diabetes has been studied by several researchers, focusing mainly on PCK1, a cytosolic isoform of this enzyme." (PMID 34203686, 2021). "PCK1 has been demonstrated to be a multifunctional gene and was closely related to gluconeogenesis, obesity, and diabetes." (PMID 32104690, 2020). "PCK1 has been established to be involved in various physiological and pathological processes, including glucose metabolism, lipid metabolism, diabetes, and tumorigenesis." (PMID 32104690, 2020). "PCK1 is the rate-limiting enzyme in gluconeogenesis and is often upregulated in patients with metabolic syndrome and diabetes mellitus." (PMID 31841108, 2019). "The Pck1 gene is mainly responsible for the regulation of gluconeogenesis and is closely related to diabetes mellitus and obesity." (PMID 30424473, 2018). "We observed that the diabetes-induced increase in renal gluconeogenic gene expression (Pck1 and Fbp1) was exacerbated by metformin." (PMID 27226136, 2016). "Recent studies have proven that the expression level of PCK1 is closely related to blood glucose control and diabetes development." (PMID 23923051, 2013). "In the liver, fasting, diabetes, carbohydrate-free diets, and high-fat diets increase Pck1 gene expression, whereas refeeding, insulin treatment, and high-carbohydrate diets decrease Pck1 gene expression." (PMID 27335827, 2013). "Widely used rodent models for genetic forms of obesity and diabetes, such as ob/ob and db/db mice, exhibit increased plasma glucocorticoids, which may drive PCK1 expression." (PMID 36918564, 2023). "In contrast, the overexpression of PCK1 in mice leads to diabetes." (PMID 37904164, 2023). "PCK1 and PCK2 have been proposed as potential diabetes and obesity-associated genes." (PMID 36360783, 2022). "However, to date, research on this enzyme with diabetes mellitus has focused primarily on PCK1 isoform." (PMID 34203686, 2021). "PCK1 is a multifunctional gene that is closely related to gluconeogenesis, obesity, and diabetes." (PMID 32104690, 2020). "Genes such as PCK1 and ALDH1A1 were associated with development of diabetes and obesity, but these genes may be linked with progression of CAD." (PMID 31881747, 2019). "These suggest PCK1 may act via glycolysis/gluconeogenesis pathways and thus affect diabetes status during oil tea treatment." (PMID 30805021, 2019). "Therefore, it is important to fully understand the mechanistic details of PCK1 regulation at the transcriptional level, since altering hepatic gluconeogenesis by modulating PCK1 gene expression could be a therapeutic approach to treat diabetes." (PMID 37595871, 2023). "Solute carrier family 2 member 4- (SLC2A4-) retinol binding protein-4- (RBP4-) phosphoenolpyruvate carboxykinase 1 (PCK1)/phosphoinositide 3-kinase (PI3K) is an adipocyte derived “signalling pathway” that may contribute to the pathogenesis of type 2 diabetes mellitus (T2DM)." (PMID 30805369, 2019). "Furthermore, research has indicated that induced expression of PCK1 may be a useful indicator for effect assessment in diabetes therapy." (PMID 30805021, 2019). "However, adjusting for diabetes diagnosis in our linear regression model did not significantly attenuate the association of PCK1 with global cognition (Beta = 0.370, p = 0.001)." (PMID 20574532, 2010). "Although the role of PEPCK-C (cytoplasmic form; PCK1) has been thoroughly investigated in diabetes and obesity 38, that of its counterpart isozyme, PEPCK-M (mitochondrial form, PCK2), remains unexplored." (PMID 35982907, 2022). "Similarly, PCK1 and G6PC are also elevated in other models of diabetes in rodents, such as the streptozotocin-diabetes model in rats." (PMID 31805072, 2019).
Obesity (48 papers, 2005 to 2025). Accumulation of substantial excess body fat. "Studies have identified PCK1 as a potential adipogenic marker, an obesity-related gene, and a gene implicated in IMF deposition." (PMID 40282015, 2025). "From the 23 known genes and 13 Riken transcripts; Dok5, Mc3r, Bmp7, and Pck1 have been associated with obesity." (PMID 25613955, 2015). "However, obesity-related to environmental and societal changes are related to this gene since single-nucleotide polymorphisms at three loci of PCK1 are related to an increased risk of obesity." (PMID 33126672, 2020). "ENOblock inhibited the pathology of diet-induced obesity by acting as a transcriptional repressor of master regulators of lipid homeostasis (Srebp-1a and Srebp-1c), gluconeogenesis (Pck-1), and inflammation (TNF-α and IL-6)." (PMID 40943261, 2025). "Even though not all studies are in the same direction, it has been described that increased fatty acid re-esterification by Pck1 overexpression at the adipose tissue leads to obesity." (PMID 38613042, 2024). "Studies have found that HHIP (hedgehog interacting protein), MUC5AC, CYP2A6, and PCK1 can promote obesity." (PMID 38137330, 2023). "Pck1 is a rate-limiting enzyme in gluconeogenesis, and overexpression of Pck1 has been previously shown to lead to obesity and an increase in triglyceride and esterification of fatty acids." (PMID 36209126, 2022). "In mice, white adipose tissue-specific overexpression of PCK1 increases the rate of glyceroneogenesis in adipose tissue and results in obesity." (PMID 33045988, 2020). "In fact, PCK1 is considered an adipogenic marker, an obesity gene, and even an IMF deposition-related gene." (PMID 33045988, 2020). "As a result, the expressionof these genes (Slc2a2, Gck, Pklr, G6P, and Pck1) was lowerin females than in males under SFD-induced obesity." (PMID 35087997, 2020). "ENOblock treatment inhibited gluconeogenesis, adiposity and obesity-related inflammation via concomitant repression of the regulatory genes Pck-1, Srebp-1a and Srebp-1c, and Tnf-a and Il-6." (PMID 30679508, 2019). "Among these, IL-6 knockout mice develop mature-onset obesity, and treatment of hepatocytes with IL-6 reduces the expression of PCK1, thus implicating IL-6 in the regulation of hepatic glucose output." (PMID 15985155, 2005). "Clostridium_sensu_stricto_1, neuromedin N, enkephalin L, Pck1, 5-hydroxy-L-tryptophan, Cxcl10 and cinnamyl alcohol may be novel biomarkers in the small intestine for obesity/obesity resistance." (PMID 36209126, 2022). "Consequently, overexpression of Pck1 in adipocytes results in obesity." (PMID 39129011, 2024). "Notably, PCK1 was gradually reduced in patients with obesity, NAFLD, and NASH." (PMID 36918564, 2023). "Different from our hypothesis, BCAA increased PPAR-γ and PCK1 expression in the high-glucose and high-fat environment and decreased the expression of FASN; this seems to confirm that BCAA has a positive effect on obesity, but an increased risk of T2DM." (PMID 35893906, 2022). "The reduction of PCK1 expression in obesity could be the consequence of the excess of triglyceride storage and the adaptation of adipocytes to get rid of some of these triglycerides throught lipolysis, perhaps mediated by glucocorticoids, which downregulate PCK1 in adipose tissue." (PMID 21182758, 2010). "It has been found that PCK1 and PCK2 can be used as candidate genes of obesity, which can participate in the synthesis of glycerophosphate and promote the accumulation of fat in human body." (PMID 35681299, 2022). "Among them, PCK1 is the rate-limiting enzyme that regulates gluconeogenesis, and CYP1B1 plays an important role in estrogen metabolism, probably corresponding to the phenotype of obesity and hormonal disturbance in PCOS patients, respectively." (PMID 34113617, 2021).
Obesity (continued). "In this analysis, we employed the Mann–Whitney U test to compare s-PCK1-Ab levels between male and female participants, type-1 and type-2 DM, with or without obesity (body mass index [BMI] ≥ 25), hypertension, CVD, dyslipidemia, and smoking or alcohol intake habits." (PMID 37904164, 2023). "To determine whether PCK1 is involved in MAFLD, we first examined hepatic gene expression in a published transcriptome dataset [Gene Expression Omnibus (GEO): GSE126848] containing samples from 14 healthy participants, 12 patients with obesity, 15 patients with NAFLD, and 16 patients with NASH16." (PMID 36918564, 2023).
hepatocellular carcinoma (46 papers, 2012 to 2025). A malignant tumor that arises from hepatocytes. "The loss of PCK1 in hepatoma cells triggered metabolic reprogramming, which led to the accumulation of oxaloacetate and increased de novo synthesis of uridine triphosphate, aiding in the production of UDP-GlcNAc." (PMID 39199296, 2024). "Regarding the underlying mechanism, PCK1 deficiency can promote hepatoma cell proliferation by dis-regulating the AMPK/CDK/Rb/E2F pathway and accelerating transition of the hepatoma cell cycle from G1 to S phase." (PMID 37062825, 2023). "We found that KAT5 was O-GlcNAcylated by OGT in PCK1-deficient hepatoma cells, and O-GlcNAcylation of KAT5 enhanced its stability." (PMID 34650217, 2021). "The AMPK activator metformin partially offset the PCK1 deficiency-mediated downregulation of p27Kip1, upregulation of pRb, promotion of G1/S transition, and acceleration of hepatoma cell proliferation." (PMID 30717766, 2019). "Importantly, we found that O-GlcNAcylation increased KAT5 stability, thereby inducing epigenetic activation of TWIST1, associated with the acquisition of a metastatic phenotype in PCK1-deficient hepatoma cells." (PMID 34650217, 2021). "Here, we describe hepatic organoid 3D cultures using hepatoma and primary donor-derived human hepatocytes and report the effects of different media conditions on key genes associated with the gluconeogenic pathway (PCK1 and G6PC)." (PMID 34943788, 2021). "Further studies are needed to verify whether TWIST1 can be acetylated by KAT5 in PCK1-deficient hepatoma cells." (PMID 34650217, 2021). "In our study, the data showed that the mRNA level of TWIST1 was upregulated in PCK1-deficient hepatoma cells, suggesting that PCK1 may transcriptionally inhibit TWIST1 by O-GlcNAcylation of KAT5." (PMID 34650217, 2021). "Then, we investigated whether loss of PCK1-mediated acceleration of the migration and invasion of hepatoma cells is dependent on KAT5." (PMID 34650217, 2021). "To determine whether the impact of PCK1 on cell proliferation is associated with cell cycle control, we performed flow cytometric analyses of PCK1-overexpression (OE) or PCK1-knockout (KO) hepatoma cells." (PMID 30717766, 2019). "Intriguingly, the progression of hepatocellular carcinoma (HCC) driven by PCK1 deficiency was suppressed by SAM supplement or S100A11 KO in vivo and in vitro." (PMID 37166978, 2023). "Importantly, we uncovered a novel mechanism that O-GlcNAcylation of KAT5, as a transcriptional regulator, epigenetically activates TWIST1 via enhancing histone H4 acetylation on the TWIST1 promoter, thereby inhibiting E-cadherin expression in PCK1-deficient hepatoma cells." (PMID 34650217, 2021). "Recently, PCK1 was reported to affect hepatocellular carcinoma (HCC) progression by regulating histone epigenetic modifications, revealing the crosstalk between metabolic reprogramming and epigenetic regulation." (PMID 39578429, 2024). "PCK1 is upregulated and required for optimal growth of human pancreatic cancer cells, hepatocellular carcinoma cells and melanoma cells." (PMID 39193344, 2024). "Moreover, in tail-vein models of lung metastasis in nude mice, fewer metastatic foci were observed in tissue sections of the lungs in PKO cells infected with lentiviral sgS100A11, illustrating that the lung metastatic potential of PCK1-deficient hepatoma cells could be facilitated by S100A11." (PMID 37166978, 2023). "PCK1 is significantly down-regulated in hepatocellular carcinoma relative to normal liver tissue, and patients with lower PCK1 expression have poor prognosis." (PMID 37062825, 2023). "Further, PCK1 is involved in metabolic changes in cancer cells and is considered a potential treatment target in hepatocellular carcinoma and clear cell renal cell carcinoma (ccRCC)." (PMID 37062825, 2023).
hepatocellular carcinoma (continued). "PCK1 overexpression accelerates colorectal xenograft growth but also antagonizes hepatoma proliferation, suggesting contextual roles of PCK1 for a given tumor type and metabolic stress, and G6PC protects glioblastoma cells from 2-deoxyglucose (2DG) treatment." (PMID 35123542, 2022). "To explore the role of PCK1 in hepatoma cell invasion and migration, we assessed the migratory potential of PCK1-knockout (PCK1-KO) PLC/PRF/5 cells as well as PCK1 overexpressing (PCK1-OE) SK-Hep1 cells." (PMID 34650217, 2021). "Together, these results show that PCK1 suppresses invasion and metastasis of hepatoma cells in vitro and in vivo." (PMID 34650217, 2021). "Specifically, lysine acetyltransferase 5 (KAT5), belonging to the MYST family of histone acetyltransferases (HAT), is highly modified by O-GlcNAcylation in PCK1 knockout hepatoma cells." (PMID 34650217, 2021). "The view that gluconeogenic enzymes are rather tumor-suppressive in cancers arising in these organs was challenged by a recent study that uncovered a novel function of PCK1 in hepatocellular carcinoma, both in vitro and in vivo." (PMID 33540663, 2021). "We found that PCK1 downregulates global O-GlcNAcylation in hepatoma cells, which is consistent with our previous study." (PMID 34650217, 2021). "In hepatocellular carcinoma, Akt-mediated activation of phosphoenolpyruvate carboxykinase 1 (PCK-1) activates SREBP proteins and promotes tumor cell proliferation." (PMID 34603386, 2021). "PCK1 is downregulated in hepatocellular carcinoma (HCC) and clear cell renal cell carcinoma and its reduced expression predicts poor prognosis." (PMID 32762776, 2020). "According to the endogenous PCK1 expression pattern in hepatoma cells, we evaluated the effect of PCK1-overexpression (OE) in SK-Hep1, Huh7, and MHCC-97H cells as well as the effect of PCK1-knockout (KO) in PLC/PRF/5 cells." (PMID 30717766, 2019). "We first monitored the protein levels of AMPK and phospho-AMPK (Thr 172; pAMPK) in PCK1-OE and PCK1-KO hepatoma cells under normal culture conditions at different time points." (PMID 30717766, 2019). "Taken together, these results indicate that PCK1 inhibits hepatoma cell proliferation by delaying G1/S transition." (PMID 30717766, 2019). "Taken together, these results demonstrate that metformin treatment efficiently inhibits the tumorigenesis of PCK1-KO hepatoma cells in nude mice through the AMPK/p27Kip1 axis." (PMID 30717766, 2019). "Next, we evaluated the effect of PCK1 gain-of-function on hepatoma cell growth in a murine subcutaneous xenograft model." (PMID 30717766, 2019). "Based on our findings, we suggest a potential model for AMPK activation and cell cycle arrest in the PCK1-induced inhibition of hepatoma cell proliferation." (PMID 30717766, 2019). "This study revealed that PCK1 negatively regulates cell cycle progression and hepatoma cell proliferation via the AMPK/p27Kip1 axis and supports a potential therapeutic and protective effect of metformin on HCC." (PMID 30717766, 2019). "Immunoblotting results revealed higher expression of PCK1 and lower expression of TXNRD1 in tumor tissues derived from the PCK1-overexpressing hepatoma cells than in GFP control group." (PMID 30619751, 2018). "As expected, the ratio of NADPH/NADP+ was increased in PCK1-overexpressing hepatoma cells, while decreased in PCK1-KO PLC/PRF/5 cells, compared to control cells." (PMID 30619751, 2018). "Gluconeogenesis mainly occurs in the liver during fasting, and previous studies have demonstrated that PCK1 acts as a tumor suppressor in hepatocellular carcinoma (HCC); however, the role of PCK1 in cancer progression remains incompletely understood." (PMID 30619751, 2018). "Huh7 PCK1-overexpressing as well as PLC/PRF/5 PCK1-knockout cell lines were used to investigate the potential function of PCK1 in hepatoma cell proliferation." (PMID 30619751, 2018).